HSPBAP1 (HSPB1 associated protein 1)
Description:
May play a role in cellular stress response.
Synonyms: PASS1; FLJ22623
Tractability: PROTAC: ubiquitination databases record sites on it; its protein half-life has been measured.
Gene: Protein-coding gene on chromosome 3 (122,739,981 to 122,793,831, reverse strand). Ensembl gene ENSG00000169087.
Subcellular location: Cytoplasm
Subcellular location (Human Protein Atlas): Mitochondria
Gene Ontology:
Molecular function: protein binding
Cellular component: cytoplasm
Genetic constraint (gnomAD): Loss-of-function variants: 15 observed, 25.53 expected, observed/expected ratio (o/e) 0.59, 90% interval 0.39 to 0.9. The upper end of that interval is the gene's LOEUF score, 0.9, which puts it in group 3 of 6, group 1 being the genes least tolerant of losing a copy. Missense variants: 389 observed, 480.34 expected, observed/expected ratio (o/e) 0.81, 90% interval 0.75 to 0.88. Synonymous variants: 154 observed, 168.43 expected, observed/expected ratio (o/e) 0.91, 90% interval 0.8 to 1.04.
Homologues: Orthologues: chimpanzee HSPBAP1 (99% identical), macaque HSPBAP1 (96% identical), dog HSPBAP1 (82% identical), pig HSPBAP1 (78% identical), rabbit HSPBAP1 (77% identical), rat Hspbap1 (74% identical), mouse Hspbap1 (73% identical), guinea pig HSPBAP1 (70% identical), tropical clawed frog hspbap1 (45% identical), zebrafish hspbap1 (44% identical), Drosophila melanogaster HSPBAP1 (21% identical). Paralogues in human: HIF1AN (17% identical), KDM8 (16% identical), TYW5 (15% identical), JMJD7 (12% identical).
Diseases named in the same sentence as HSPBAP1 in open-access papers:
HSPBAP1 is named in the same sentence as 10 diseases in open-access papers, as found by Europe PMC text mining. Sharing a sentence is not in itself a finding about the gene and the disease. The quoted sentences say what the papers report.
epilepsy (2 papers, 2011 to 2021). A brain disorder characterized by episodes of abnormally increased neuronal discharge resulting in transient episodes of sensory or motor neurological dysfunction, or psychic dysfunction. "The neuroprotective role of Hsp27 in epilepsy was further confirmed by the abnormal expression of HSPBAP1 (heat shock 27-kDa associated protein 1), observed in the neocortex of patients with intractable epilepsy (IE)." (PMID 34445306, 2021). "Among these are RACK1 (involved in neuronal excitation), TSC1 (control of axon formation, epilepsy), APP (seizure susceptibility), HSPBAP1 (upregulated in epilepsy patients) and p190 RhoGAPs (involved in neuronal differentiation and process outgrowth)." (PMID 22016787, 2011).
Insulin resistance (1 paper, 2024). Increased resistance towards insulin, that is, diminished effectiveness of insulin in reducing blood glucose levels. "A histone demethylase HSPBAP1 may be involved in regulating stress responses in cells by inhibiting HSP27, which has been suggested to prevent obesity-induced insulin resistance." (PMID 38483771, 2024).
prostate carcinoma (1 paper, 2022). A carcinoma that arises from epithelial cells of the prostate gland. "HSPB-associated protein 1 (HSPBAP1) exhibits oxidoreductase activity, and its overexpression has been observed in prostate cancer samples." (PMID 35629968, 2022).
bacterial infections (1 paper, 2023). "Variable selection using FS-PLS identified 4 genes distinguishing MIS-C from KD, viral and bacterial infections: HSPB1 Associated Protein 1 (HSPBAP1), Vacuolar Protein Sorting-Associated Protein 37C (VPS37C), Transforming Growth Factor Beta 1 (TGFB1) and MX Dynamin Like GTPase 2 (MX2)." (PMID 37255317, 2023).
neurological diseases (1 paper, 2021). "This provides support about that gene HSPBAP1 could be involved in the mechanism of brain pathology tangles and other neurological diseases such as intractable epilepsy." (PMID 33798195, 2021).
HSPBAP1 also shares sentences with these, for which no sentence is quoted: cystic fibrosis (1 paper); infection (1); neuroblastoma (1); Obesity (1); parasitic infection (1).